MMP3 (matrix metallopeptidase 3)
Diseases named in the same sentence as MMP3 in open-access papers (continued):
Sharing a sentence is not in itself a finding about the gene and the disease.
tumor (continued). "Moreover, we found that RANKL could promote the expression of MMP1, MMP3 and MMP9, which indicated that increased expression of MMPs was involved in the process that RANKL promoted tumor invasion and migration via NF-κB pathway." (PMID 25268581, 2014). "Study using breast cancer samples demonstrates that the expressions of MMP-1, MMP-2, MMP-3, MMP-9, urokinase-type PA, and tissue-type PA, and inhibitors (TIMP-1 and TIMP-2) were stronger or equivalent in tumor cells than in fibroblasts or inflammatory cells within the tumor section." (PMID 21152266, 2010). "Interestingly, expression analysis of MDA-byb1 and -hyb2 tumor hybrids revealed appropriate upregulation of EMT-associated genes, such as SLUG, collagen, fibronectin, N-cadherin, MMP3, and MMP9, possibly indicating that tumor hybrids might have acquired a mixed E/M state." (PMID 35562905, 2022). "In immune analysis, ICAM1, IL1B, IL-6, MMP1, MMP3, MMP9, and SERPINE1 all showed positive correlations with most immune cells, implying that CC and MF may exert an antitumor activity by interacting with these genes and immune cells, and thus control tumor development." (PMID 35783510, 2022). "However, roles of MMP3 within tumor growth and EVs have not unveiled." (PMID 32429403, 2020). "Thus, while tumor-derived fibroblasts are stimulatory of tumor invasion, whether or not they are of the MMP-3 5A/5A genotype is more important." (PMID 17922906, 2007). "Unlike common anticancer agents, BB94 is a potent extracellular inhibitor of MMP-1, MMP-2, MMP-3, MMP-7, and MMP-9, and thus, it should be released in the extracellular space rather than in tumor cells." (PMID 35440570, 2022). "Though OPN was not essential for tumor formation, it was indicated that OPN is involved in early stage intestinal tumorigenesis in part by upregulation of MMP-3, MMP-9, and MMP-13, and infiltration of macrophages and neutrophils." (PMID 28505114, 2017). "Several angiogenesis-related genes like MMP1, MMP3, SFRP2, CXCL8, SERPINE1 and TNFAIP6 were up-regulated in tumors with necrosis, as identified among genes differentially expressed between tumor samples with and without necrosis." (PMID 26485755, 2015). "Fibroblast invasion-promoting capacity (IPC) was analyzed in relation to donor type (tumor or non-tumor patient), MMP-1, MMP-3, and MMP-9 SNP genotype and MMP activity using independent samples t test and analysis of variance." (PMID 17922906, 2007). "In the MDA-MB-231 spleen metastasis, the tumour cell showed high MT1-MMP (3+), and low MMP-3 expression (1+), but no detectable MMP-1 gene expression (0+)." (PMID 16430785, 2006). "Plasma concentrations of MMP1, MMP3, MMP9, TIMP2, and MTC1 did not correlate to tumour stage and grade, but also to lymph node involvement or distant metastasis (data not indicated)." (PMID 16901349, 2006). "Plasma concentrations of MMP1, MMP3, MMP9, TIMP2, and the MTC1 did not correlate to tumour stage, grade, lymph node involvement, or distant metastasis." (PMID 16901349, 2006). "Moreover, the tumor growth patterns seen in wild-type mice were maintained in SCID mice, suggesting that modulation of MMP3 expression did not simply impact tumor growth by subverting adaptive immunity." (PMID 26008967, 2015). "In this study, we aimed to correlate the expression of DSPP, OPN and BSP as well as three SIBLING-partners, matrix metalloproteinase-2 (MMP-2), matrix metalloproteinase-3 (MMP-3), and matrix metalloproteinase-9 (MMP-9), at histologically-negative margins of OSCCs with tumor recurrence." (PMID 22410369, 2012). "Separate analyzes of MMP1, MMP2, MMP3, MMP9, TIMP1, TIMP2, and MTC1 in plasma do not allow a prognostic prediction for tumour grading, staging, or metastasis, but certain combinations could be very helpful." (PMID 16901349, 2006).
tumor (continued). "To understand whether exosomes were involved in the regulation of MMP3 protein levels and MMP9 activities in tumor patients, we analyzed MMP3 protein levels and MMP9 activities in lung tumor tissues from obese tumor patients with or without amiloride treatment." (PMID 29137230, 2017). "After inhibition of 3T3-A-EXO uptake by cytochalasin D, increased MMP9 activity in 3LL tumor cells could not be detected, suggesting that MMP3 in 3T3-A-EXO cannot directly induce MMP9 activation and fusion of 3T3-A-EXO and that 3LL tumor cells are required for this process." (PMID 29137230, 2017).
cancer (321 papers, 2004 to 2026). A tumor composed of atypical neoplastic, often pleomorphic cells that invade other tissues. "The MMP-3 rs3025058 promoter polymorphism has been investigated in several diseases, including certain cancers, cardiovascular conditions, musculoskeletal injuries, and other diseases." (PMID 40724896, 2025). "Among them, MMP1 and MMP3 are known to be associated with cancer growth, invasion, and metastasis, and they were also increased in Huh7 cells after arsenite exposure." (PMID 39756915, 2024). "The increased expression of MMP-11 and MMP-3 further indicates that macrophage-CM can increase adipocyte delipidation and cancer association." (PMID 36551185, 2022). "MMP3 overexpression is associated with cancer metastasis, development of pre-malignant and malignant lesions, spontaneous neoplastic progression, and genomic instability." (PMID 35453667, 2022). "MMP3 is positively correlated with endothelial cell infiltration (Rho = 0.285, p = 3.48e-03) and cancer-associated fibroblasts (Rho = 0.242, p = 1.39e-02) infiltration." (PMID 36226170, 2022). "The first network showed hubs around TNF and MMP3 and was associated with cancer, cellular movement, and connective tissue disorders." (PMID 33059716, 2020). "The MMP3 gene has also been implicated as a contributor to cancer progression and reported to be responsible for inducing epithelial-mesenchymal transition and increasing cell spreading." (PMID 33324695, 2020). "Recently, MMP3 have been considered as potential diagnostic or prognostic biomarkers in some types of cancer, especially in head and neck squamous cell carcinoma 8-11." (PMID 32922541, 2020). "The MMP3 gene encodes the matrix metallopeptidase 3 and is generally associated with multiple steps of cancer development, invasion and metastasis." (PMID 30323202, 2018). "Full length RON activation cause increases in ESM1 (endocan) that has previously been associated with pro-angiogenic cytokine production and cancer metastasis and MMP3, which is associated with increased cell tumorigenicity." (PMID 27323855, 2016). "For example, the 5A vs. 6A single nucleotide polymorphism at position −1171 upstream from the transcription start site has been associated with over-activation of MMP3 promoter activity and higher incidences of cancer." (PMID 26008967, 2015). "MMP-3 also called stromelysin-1 was one of the first proteinases found to be associated with cancer." (PMID 26019576, 2014). "In our comprehensive meta-analysis, MMP1 (−1607)1G/2G, MMP7 (−181) A/G and MMP9 (−1562) C/T were shown to increase the risk of cancer metastasis, whereas MMP3 (−1171) 5A/6A was protective in metastasis." (PMID 22348060, 2012). "It has been documented that the 2G type SNP of MMP-1 confers increased susceptibility to colorectal, ovarian, lung, endometrial, renal cell and head and neck cancers; and the 5A type SNP of MMP-3 is associated with an increased susceptibility to breast cancer." (PMID 17919326, 2007). "In addition, MMP-3 is associated with cancer progression as its upregulation is reported in different cancers, such as advanced urothelial carcinoma, small cell lung carcinoma, and high-grade endometrial sarcoma." (PMID 36445856, 2022). "It was demonstrated that MMP-3 was associated with the metastatic potential of various cancers." (PMID 34441979, 2021). "High expression of MMP3 in many cancers has been associated with poor prognosis." (PMID 34414229, 2021). "MMP3 polymorphisms are linked with cancer development in COPD patients." (PMID 33005006, 2020). "Finally, we observed that CCL20 and IL-17A levels were both positively associated with levels of CD44 and MMP3, which are closely related to cancer progression." (PMID 31387598, 2019).
cancer (continued). "Western blot analysis revealed up-regulation of pro-apoptotic protein BAX, along with the down-regulation of anti-apoptotic proteins (BCL-XL, Survivin), migration associated proteins (p-FAK, MMP-3) and cancer stem cell (CSC) markers (CD44, Oct-4), which was probably mediated by AKT/c-Jun pathway." (PMID 28036386, 2016). "A recent study also showed that BMP4 induces the expression of multiple MMPs, including MMP3 and MMP14, in mouse mammary fibroblasts and it also modestly induces the expression of MMP3 in cancer associated human mammary fibroblasts and to a greater degree in normal human mammary fibroblasts." (PMID 24053318, 2013). "Eight studies investigated MMP3 (−1171) 5A/6A and its association with cancer metastasis." (PMID 22348060, 2012). "Similar to AKT, MMP3 can also cause epithelial–mesenchymal transition in cancer." (PMID 17242701, 2007). "CAFs can contribute to MMP3 upregulation in cancer cells by secreting factors that influence MMP3 expression and remodeling the extracellular matrix, further influencing MMP3 activity." (PMID 40362252, 2025). "Mmp3 plays a key role in tissue remodeling, wound healing, and pathological processes such as inflammation and cancer development." (PMID 40335839, 2025). "The CCL20/CCR6 axis contributes to the activation of NF-kB and secretion of MMP-3, which promote cancer cell invasion and migration." (PMID 40150133, 2025). "In contrast, MMP-3 levels were significantly lower in cancer patients relative to the dysplasia group, suggesting a distinct behavior compared to the other metalloproteinases." (PMID 41462922, 2025). "Combining MMP3 therapy with oncolytic virus therapy presents a promising avenue in cancer therapeutics." (PMID 39431237, 2024). "We selected eight candidates (CST4, CCL20, CX3CL1, CXCL5, CXCL8, GDF15, CCL5 and MMP3) that play an important role in cancer pathogenesis for further study." (PMID 38385965, 2024). "To further demonstrate the generality of the EDS approach, we developed highly selective blockers of the proteolytic activation to two other MMPs (i.e., MMP1, MMP3) that play roles in multiple cancers and are thought to be promising cancer targets." (PMID 38683990, 2024). "Taken together, the APRIL/TNFSF13, BAFF/TNFSF13B, and MMP-3 pathway plays a critical role in the regulation of the immune system, and dysregulation of this pathway can lead to the development of cancer." (PMID 37511338, 2023). "This factor can promote cancer cell metastasis by dissolving the cancer cell matrix, while TsIIA has long been proven to inhibit the expression of MMP-3/9 in HCC, which seems to be partly due to the blocking of the activation of NF-kappa B." (PMID 36798821, 2023). "Transcriptome analysis revealed that CHRM3 knockdown significantly reduced an array of classic factors in cancer invasive growth including MMP1/MMP3/MMP10/MMP12 and CXCL1/CXCL5/CXCL8." (PMID 37744266, 2023). "When CCT4 is activated, the ERBB signal pathway is inhibited, the apoptosis is enhanced, the expression of MMP3/9 is downregulated, and cancer cells’ invasion and metastasis ability is decreased." (PMID 37058032, 2023). "MMP-3 is a member of the matrix metalloproteinase family, playing important roles in morphogenesis and tissue remodeling, as well as diseases such as cancer, fibrosis, etc.." (PMID 37217992, 2023). "By manipulating the ECM, MMP3 is involved in oncogenesis, cancer cell proliferation, and invasion, and this explains the factor of poor survival in PC." (PMID 37727377, 2023). "MMP3 belongs to the Zinc-dependent endopeptidase family, primarily secreted by cancer cells, connective tissues, endothelial cells, immune cells like mononuclear macrophages, and neutrophils." (PMID 36742294, 2023). "MMP-3 promotes cancer invasion and metastasis through the enzymic breakdown of the basal membrane and extracellular matrix." (PMID 36211828, 2022). "Blocking MMP-3 expression inhibited gemcitabine resistance and cancer progression in cellular and animal models." (PMID 36211828, 2022).
cancer (continued). "MMP-3, a member of the matrix metalloproteinase family, is well-known as a vital factor in cancer metastasis and invasion." (PMID 36211828, 2022). "The MMP-3 expression was elevated in naturally generated gemcitabine-resistant cancer cells than in normal cancer cells." (PMID 36211828, 2022). "MMP3 is a widely studied matrix metalloproteinase that can regulate cell migration and invasion of cancer cells." (PMID 35399729, 2022). "Elevated MMP-3 expression was positively related to cancer invasion and gemcitabine resistance in PDA cells and gemcitabine resistant PDA cells." (PMID 36211828, 2022). "MMP-3 ablation, in vitro and in vivo, suppressed cancer cells proliferation and reduced bone metastasis." (PMID 35669415, 2022). "A significantly lower content of MMP-3 in both cancer grades in contrast to the distinctive growth of MMP-10 was observed." (PMID 36231910, 2022). "Univariate Cox regression analysis identified four genes (CCNB1, CCNA2, IL1A, and MMP3) that significantly affected patient survival based on the 27 anticolon cancer targets of THCQF." (PMID 35479514, 2022). "MMP3 has also been detected in the nucleus of the cell to control nuclear events, such as apoptosis and cancer progression." (PMID 36553576, 2022). "In conclusion, a high glucose environment induces gemcitabine resistance and cancer invasion via ROS/MMP-3 signaling pathway." (PMID 36211828, 2022). "The genes observed in this network (CEACAM1, IGF1, MET, MMP1, MMP3 and WNT5A) were upregulated in cSII/III and are known to be linked to invasive properties in several other cancer types." (PMID 35022523, 2022). "Among them, the member of histone deacetylase (HDAC), Hdac11, was significantly downregulated in the inflammation-cancer link, whereas, Mmp3, the member of matrix metalloproteinases, was dramatically upregulated." (PMID 35399729, 2022). "MMP3, 7, and 9, among other genes from the same family, were studied extensively and were found to play roles in a variety of cancers and diseases through various pathways; they have even been used as anti-cancer drugs." (PMID 36555553, 2022). "Inhibiting NOX4 expression effectively suppressed MMP-3 expression, gemcitabine resistance, and cancer invasion." (PMID 36211828, 2022). "The mRNA levels of Hdac11 were dramatically decreased, whereas Mmp3 was increased, indicating that Hdac11 is downregulated and Mmp3 is upregulated in the inflammation-cancer link." (PMID 35399729, 2022). "Some MMPs, such as MMP-3 and -8, exhibit protective roles in cancer, and the same MMP can be pro-tumorigenic or anti-tumorigenic depending on the cell type in which it is expressed or the stage of cancer." (PMID 36741729, 2022). "HOXB4 acts as a transcription factor to directly evoke or inhibit the expression of genes including Snail, Twist, and MMP3 involved in regulation of carcinogenesis and cancer metastasis." (PMID 35211403, 2022). "MMP-3 participates actively in cancer progression since it inhibits the Wnt5b favoring the activation of the canonical Wnt signaling pathway to induce cancer stem cells differentiation and expansion." (PMID 36213817, 2022). "The extracellular domain of cell adhesion factor E-cadherin can be cleaved by MMP3 directly, which facilitates the metastasis of cancer cells." (PMID 36313626, 2022). "In vitro, MMP-3-enriched extracellular vesicles from a metastatic murine cancer cell line LuM1 activated the promoter and production of the matricellular protein CTGF (connective tissue growth factor, aka CCN2) in “recipient” cells." (PMID 35163805, 2022). "Given the role of MMP-3 in cancer progression and metastasis, a study with 73 CRC patients who underwent minimally invasive colorectal resection investigated the relationship between increased plasma MMP-3 and residual metastases after surgery." (PMID 36776395, 2022).